CST5 (cystatin D)
Diseases named in the same sentence as CST5 in open-access papers (continued):
Sharing a sentence is not in itself a finding about the gene and the disease.
pseudotumor cerebri (1 paper, 2024). Idiopathic intracranial hypertension is a neurological disorder characterized by isolated increased intracranial pressure manifesting with recurrent and persistent headaches, nausea, vomiting, progressive and transient obstruction of the visual field, papilledema. "Enrichment analysis using DisGeNET revealed that genes related to Cystatin D expression in the brain were associated with childhood astrocytoma and pseudotumor cerebri, whereas genes related to FGF21 were linked to gout-related diseases." (PMID 38784036, 2024).
renal dysfunction (1 paper, 2024). "Conversely, CKD itself appears to instigate alterations in CST5 levels, revealing a bidirectional relationship between renal dysfunction and immune responses." (PMID 38703294, 2024).
Sleep apnea (1 paper, 2017). An intermittent cessation of airflow at the mouth and nose during sleep is known as sleep apnea. "Suggestive associations of symptoms of sleep apnea were observed with 11 rare variants (located in KANK2, LCN6, TRAF3, PLEK, HIF1A, SLC45A3, ERCC1/CD3EAP, MRGPRE, GRAMD4, TYW5, CST5)." (PMID 29093733, 2017).
squamous cell lung carcinoma (1 paper, 2025). A carcinoma arising from squamous bronchial epithelial cells. "No causal relationships were found for genetically predicted Cystatin B (ebi‐a‐GCST90085722), Cystatin B (prot‐b‐3), Cystatin D, Cystatin F, Cystatin M (prot‐a‐703), or Cystatin M (prot‐a‐704) with squamous cell lung carcinoma (all p > 0.05)." (PMID 40641363, 2025).
tumor (15 papers, 2015 to 2026). "CST5, which encodes an inhibitor of several cysteine proteases of the cathepsin family, is a candidate tumour suppressor gene." (PMID 36408648, 2023). "CST5, a cysteine protease inhibitor, has been reported to be associated with tumour suppression, but there was little research focusing on the effect of CST5 on OP." (PMID 31402549, 2019). "Proteomic signatures highlighted AREG, JUN, and ITGA6 can track skin damage, while CST5 and PRDX1 correlated with the preservation." (PMID 42143604, 2026). "CST5 is identified as a significant mediator of tumor suppression by mediating mesenchymal-epithelial transition (MET) in CRC cells (Hünten and Hermeking, 2015)." (PMID 41164825, 2025). "One possible explanation is that CST4 and CST5, both members of the cystatin family, are expressed and regulated differently in salivary glands compared to tumor cells or blood components." (PMID 41164825, 2025). "Cystatin D modulates immune responses and inflammation, key processes in tumor development." (PMID 40641363, 2025). "Since SNAIL-mediated repression of CST5 is abrogated by calcitriol treatment, calcitriol may inhibit tumor progression even in cells that show high SNAIL expression and therefore have a high tumorigenic potential." (PMID 26158294, 2015).
cancer (6 papers, 2018 to 2025). A tumor composed of atypical neoplastic, often pleomorphic cells that invade other tissues. "The KM survival curves showed that CST5 and CST4 were risk factors, and high CST5 and CST4 levels in cancer tissue were associated with worse PFS, compared with the low-risk group (P < 0.05)." (PMID 41164825, 2025). "In a series of elegant experiments, it was demonstrated that cystatin D had effects on several cellular events, including proliferation, migration, and expression of cancer‐promoting genes." (PMID 32810913, 2020). "Additionally, CST4/CST5 may be consumed or degraded more rapidly in the oral cavity environment of cancer patients due to shifts in oral microbiota or protease activity." (PMID 41164825, 2025). "The biomarkers most significantly associated with short-term mortality were IL-6, IL-10, IL-8, MCP-1 (mainly inflammatory markers), FGF-21, ST1A1, 4E-BP1 and CST5 (classified by OLINK as cardiovascular markers) and FGF-23 (classified as a cancer marker)." (PMID 36209229, 2022).
infection (2 papers, 2009 to 2025). The state of being infected such as from the introduction of a foreign agent such as serum, vaccine, antigenic substance or organism. "We noted interestingly that CD1 and BALB/c mice (+PVL phenotype) cleared WT CST5 infection much more effectively compared to SKH1 or C57BL/6 mice (no PVL phenotype), but developed significantly larger lesions compared to SKH1 or C57BL/6 mice." (PMID 19633710, 2009).
kidney disease (2 papers, 2024). "Our study corroborates these findings, elucidating a direct causal link between CST5 and CKD, thereby expanding the understanding of cystatin D beyond its established biological functions and into the realm of kidney disease pathogenesis." (PMID 38703294, 2024).
cardiovascular disease (1 paper, 2023). "Furthermore, many of the age-associated proteins such as CST5, CCL23, SLAMF1, MMP-1, MCP-1, and CDCP1 have been linked to chronic diseases such as cardiovascular disease and neurocognitive decline in the general population." (PMID 37672793, 2023).
CST5 also shares sentences with these, for which no sentence is quoted: systemic mastocytosis (2 papers); gingivitis (1); gout (1); hepatocellular carcinoma (1); HIV-1 infection (1); IgA nephropathy (1); kidney (1); male infertility (1); melanoma (1); Obesity (1); pancreatic cancer (1); primary sclerosing cholangitis (1); sarcoidosis (1).